IL6 (interleukin 6)
Diseases named in the same sentence as IL6 in open-access papers (continued):
Sharing a sentence is not in itself a finding about the gene and the disease.
Obesity (continued). "Obesity results in a proinflammatory state starting in the metabolic cells (adipocyte, hepatocyte, or myocyte) and also recruiting immune cells with the consequent release of inflammatory cytokines (TNF-α, IL-6, adiponectin, etc.)." (PMID 22523672, 2012). "Inflammation measured by mRNA expressions of IL-6, MMP-9, PAI-1 and leptin and protein expression of NF-κB was higher, whereas anti-inflammation measured by mRNA expressions of adiponectin and INF-γ was lower in obesity than in control and OR (all p<0.003)." (PMID 22784636, 2012). "Cytokines, such as IL-6 and TNF-α, are increased in obesity and correlate with insulin resistance." (PMID 22518191, 2012). "In the early stage of HF-diet–induced obesity, inflammation is increased because of inflammatory cell infiltration, and circulating cytokines such as TNF-α and IL-6 are elevated; the latter further activates inflammatory signaling in the liver, which in turn, promotes hepatic lipid accumulation." (PMID 22720061, 2012). "It has also been suggested that, as TNF-α can trigger IL-6 release, increased systemic IL-6 levels may reflect enhanced adipose tissue production of TNF-α, the actual driver behind obesity-related insulin resistance." (PMID 22615828, 2012). "The strong positive association between amylin and the risk of MetS was independent of the well established risk factors, including obesity, inflammatory markers (CRP and IL-6) and insulin resistance in apparently healthy Chinese population." (PMID 21935471, 2011). "Obesity promotes insulin resistance by resulting in a state of chronic inflammation that involves production of proinflammatory cytokines (TNF-α, IL-6), an increase in the number of macrophages, and activation of a complex cascade of signaling events in muscle, fat and liver tissues." (PMID 21738773, 2011). "The production of IL-6 and TNF-α is increased in adipose tissue of obese individuals, and adipose tissue inflammation is considered to represent an important pathogenetic factor in the development of obesity-related complications such as insulin resistance." (PMID 21197447, 2010). "Systemic inflammation is markedly evident in a number of human and mouse models of obesity, as determined by increased plasma levels of inflammatory cytokines such as tumor necrosis factor-α (TNF-α), interleukin-6 (IL-6), and monocyte chemoattractant protein-1 (MCP-1)." (PMID 20508825, 2010). "In the present study we did not observe differences of serum concentrations of TNF-α, IL-6, and leptin between depressive and nondepressive patients with obesity." (PMID 19587822, 2009). "Resistin mRNA expression is increased in PBMC from DM2 women, together with increased expression of the inflammatory cytokines IL-1β, TNF-α, and IL-6, independent of obesity." (PMID 19125180, 2008). "Obesity transforms adipose tissue into a pro-inflammatory endocrine organ, where hypertrophic adipocytes release adipokines such as leptin alongside cytokines including TNF-α and IL-6, potentially contributing to macrophage polarization toward an M1 phenotype and activating NF-κB signaling pathways." (PMID 42188056, 2026). "Chronic low-grade inflammation and upregulation of pro-inflammatory cytokines (e.g., IL-6, TNF-α) in the comorbidity of hypertension and insulin resistance amplify the glomerular and interstitial inflammatory injury triggered by dysglycemia, dyslipidemia, and obesity." (PMID 41601932, 2026). "Compared with non-obese patients with PCOS, those with obesity demonstrated more severe inflammatory responses, including increased levels of IL-6, TNF-α, neutrophil-to-lymphocyte ratio (NLR), high-sensitivity C-reactive protein (hs-CRP), and mean platelet volume (MPV) levels." (PMID 41239503, 2025). "Notably, IL-6, IL-8, AEA, OEA, MMP-2, and TNF-α were elevated in individuals with MUO and also correlated positively with BMI, further reinforcing the link between chronic inflammation and obesity." (PMID 40153192, 2025).
Obesity (continued). "In mice, obese mice showed greater neutrophilic airway inflammation with elevation of IL-6 levels in broncho-alveolar lavage (BAL) fluid, which was reduced by neutralizing antibodies for IL-6, indicating that IL-6 also has the potential to mediate obesity-induced asthma severity." (PMID 40589493, 2025). "In obesity, adipose tissue becomes metabolically dysregulated and secretes elevated levels of pro-inflammatory cytokines, such as tumor necrosis factor-alpha (TNF-α) and interleukin-6 (IL-6), along with altered levels of adipokines including leptin and adiponectin." (PMID 40690028, 2025). "The model exhibits pronounced cardiometabolic dysfunction, including obesity, insulin resistance, dyslipidemia, QTc prolongation, reduced QRS amplitude, and elevated markers of myocardial injury (Troponin T, CK-MB) and systemic inflammation (IL-6, IL-1β, TNF-α) (p < 0.05)." (PMID 41309777, 2025). "Moreover, obesity would alter levels of numerous molecules, such as TNFα, DKK1, sclerostin, IL-6, serotonin, and advanced glycation end products, which could inhibit osteoblastogenesis." (PMID 40685394, 2025). "However, it is crucial to consider that chronically elevated IL-6 levels, common in both SCZ and obesity, may create a vicious cycle, with each condition exacerbating the other." (PMID 41007867, 2025). "Moreover, the association between carnitine and obesity may also involve pathways of oxidative stress (e.g., inhibition of NF-κB expression) and chronic low-grade inflammation (e.g., decreased levels of IL-6, TNF-α, and CRP), which are hallmarks of obesity." (PMID 41291687, 2025). "A recent study also reported that coffee consumption during HFD-induced obesity improved glucose intolerance in mice, which was accompanied by reductions in macrophage infiltration and expression of IL-6 and TNF-α in adipose tissue, as well as in plasma IL-6 levels." (PMID 40565007, 2025). "Another important aspect is the increased macrophage population on the placenta of women with obesity compared to pregnant women with normal weight, characterized by increased CD14+, CD68+, and CD11b+ markers, as well as increased gene expression of cytokines IL‐1, TNF‐α, IL‐6." (PMID 41452351, 2025). "It has also been determined that obesity, both in children and adults, induces a state of low-grade inflammation and metabolic alterations, such as increased plasma leptin, hyperinsulinemia, and elevated production of tumor necrosis factor-alpha (TNF-α) and interleukin-6 (IL-6), among others." (PMID 40531756, 2025). "Obesity, a central driver, may result in adipose tissue dysfunction, leading to chronic, low-grade inflammation due to the secretion of pro-inflammatory cytokines, such as Tumor Necrosis Factor alpha (TNF-α) and interleukin-6 (IL-6)." (PMID 41406476, 2025). "Since the appropriate inflammatory biomarkers in obesity are not well defined, we selected and examined an array of diverse biomarkers (IL6, IL8, PCT, TREM-1, and uPAR), of different cellular sources and pathophysiological roles to cover diverse etiology-based types of inflammations." (PMID 40003433, 2025). "The inflammation hypothesis suggests that obesity is a chronic inflammatory state, and inflammatory factors such as TNF-α, interleukin-1β (IL-1β), and IL-6 can decrease tissue sensitivity to insulin and lead to pathological changes in pancreatic β-cell function." (PMID 40842495, 2025). "People with obesity, including those without T2D, have higher IL-6 levels." (PMID 40002771, 2025). "Children with and without obesity have shown increased IL‐6 concentrations immediately post‐exercise and an hour into recovery in response to moderate‐intensity aerobic exercise, high‐intensity interval training exercise, and moderate‐intensity resistance exercise." (PMID 40243109, 2025).
Obesity (continued). "The results of our study revealed that concentrations of TNF-α and IL-6 decreased significantly after resuscitation in BRS and usage of PEEP, suggesting that the combined use of the two measures could reduce inflammatory response in patients with obesity." (PMID 39722113, 2025). "In the context of obesity, adipocytes undergo hypertrophy, which subsequently leads to an increased recruitment of immune cells, such as M1 macrophages, and inflammatory mediators within the tissue, including tumor necrosis factor alpha (TNF-α), interleukin 6 (IL-6), and interleukin 1β (IL-1β)." (PMID 41149048, 2025). "However, in pathological conditions—such as obesity or metabolic syndrome—elevated leptin levels become pro-inflammatory, increasing the production of pro-inflammatory cytokines, such as TNF-α and IL-6, exacerbating vascular inflammation and contributing to the development of atherosclerosis." (PMID 40943241, 2025). "In addition, inflammatory cytokines associated with obesity-related immune responses, including TNF-α, IL-6, and IL-10, were not measured, limiting our understanding of the immunometabolic effects of LA-1." (PMID 40732971, 2025). "As obesity progresses, the adipokine secretion profile becomes imbalanced, with increases in pro-inflammatory molecules such as resistin, tumor necrosis factor-alpha (TNF-α) and interleukin-6 (IL-6) among others and decreases in protective molecules like adiponectin, omentina-1, etc.." (PMID 41155642, 2025). "This supports the notion that IL-6 may impair β-cell function and insulin signaling, contributing to hyperglycemia in the absence of significant obesity." (PMID 41523554, 2025). "However, it has also been shown that high-intensity interval exercise does not affect insulin, lipid profile, C-reactive protein, and interleukin-6 in people with overweight or obesity." (PMID 40003575, 2025). "Interestingly, the IL-6 levels of people with obesity, including those without T2DM, are therefore higher." (PMID 40002771, 2025). "Importantly, local WAT inflammation can induce regional insulin resistance through cytokine release (e.g., IL-1β, TNF, IL-6) without requiring systemic cytokine elevation, underscoring a paracrine component of muscle–adipose crosstalk in obesity." (PMID 41002965, 2025). "In obesity, the adipose tissue functions as an active endocrine organ, secreting components of the RAAS, including angiotensin II and various pro-inflammatory cytokines, such as IL-1β, IL-6 and TNF-α and adipokines, contributing to chronic, low-grade inflammation and IR." (PMID 41020888, 2025). "Additionally, an eight-week trial of late TRE with longer fasting durations (18 and 20 h) did not alter TNF-α or IL-6 compared to a control in adults with obesity." (PMID 39861451, 2025). "Lean diabetics demonstrated relatively higher adiponectin but elevated inflammatory markers, particularly CRP and IL-6, suggesting that chronic low-grade inflammation and β-cell dysfunction, rather than obesity-related insulin resistance, are central to disease pathogenesis in this subgroup." (PMID 41523554, 2025). "In conditions such as obesity, aging, insulin resistance, dyslipidemia, or chronic oxidative stress, PVAT undergoes phenotypic switching, adopting a pro-inflammatory profile leading to increased secretion of leptin, IL-6, and TNF-α, while decreasing adiponectin levels." (PMID 40943241, 2025). "In obesity, adipose tissue chronic inflammation promotes the secretion of proinflammatory cytokines, such as tumor necrosis factor alpha (TNF-α), interleukin (IL)-1β, IL-6, IL-17, and interferon (IFN)-γ, which prolong the extension of chronic inflammation in adipose tissues." (PMID 40863244, 2025). "In addition, CRP regulates the expression of key adipokines and inflammatory mediators, including adiponectin, TNF-α, leptin, IL-6, and PPAR-γ, which may underpin its involvement in insulin resistance, obesity, and metabolic syndrome." (PMID 40001459, 2025).
Obesity (continued). "Higher induction of proinflammatory cytokines, IL-6 and IL-18, may indicate stronger early inflammatory response in non-responders than in females with obesity." (PMID 41488663, 2025). "Notably, the absence of IL-6-BMI associations in our cohort contrasts with meta-analytic findings in general populations, suggesting that schizophrenia-specific factors, such as prolonged antipsychotic exposure or genetic susceptibility, may alter canonical obesity-inflammation pathways." (PMID 40791199, 2025). "Besides augmenting mechanical stress, obesity often correlates with chronic, low-grade inflammation, which heightens the activity of proinflammatory cytokines (e.g., TNF-α, IL-6), exacerbating ECM breakdown and reduced proteoglycan/collagen synthesis in the disc." (PMID 40421015, 2025). "Obesity may contribute to OME through the following mechanisms: alterations in cytokine levels, such as IL-6, TNF-α, and fibrinogen activator inhibitor-1 (FAI-1); alterations in host immunity; induction of gastroesophageal reflux; and alterations in pharyngeal tube structure." (PMID 38440649, 2024). "Obesity is also known to be accompanied by low-grade chronic inflammation showing increased proinflammatory chemokines and cytokines, such as monocyte chemotactic protein-1 (MCP1), interleukin-1β (IL-1β), interleukin-6 (IL-6) and tumor necrosis factor-α (TNF-α)." (PMID 38464534, 2024). "Moreover, the assessment of IL-6 levels was found to significantly differentiate between patients with obesity without MASLD and normal-weight individuals." (PMID 38732626, 2024). "A study reported a significant decrease in IL-6 and a significant increase in adiponectin following a short-term lifestyle intervention among children with obesity, however, we could not produce similar findings." (PMID 39523406, 2024). "However, three other studies reported no change in IL-6 levels after 7–8 h of uninterrupted sitting in healthy adults, adults with overweight or obesity, and postmenopausal females with rheumatoid arthritis." (PMID 39088575, 2024). "Additionally, the study revealed that children with SDB exhibited severity-dependent increases in plasma C-reactive protein (CRP) and IL-6 levels, regardless of their obesity status." (PMID 38672697, 2024). "Additionally, BMI was used instead of waist circumference to assess obesity, and direct measurements of cytokines like IL-6 and TNF-α were not performed, limiting mechanistic insights." (PMID 39070321, 2024). "An important mention is that the pro-inflammatory phenotype M1 in obesity is different from the phenotype of M1 macrophages in acute inflammatory reactions, in that M1 ATMs express lower levels of pro-inflammatory CKs like TNF-α and IL-6 compared to the classical acute inflammatory M1 response." (PMID 39063610, 2024). "Inflammation of the adipose tissue is mediated by inflammatory cytokines, such as IL1-1β, IL-6, IL-8, IL-10, IL-12, and Tumor Necrosis Factor (TNF-α), as well as chemokines including MCP-1, which are produced by M1 macrophages in the adipose tissue of individuals with obesity." (PMID 38396489, 2024). "Adipose tissue remodeling during obesity provides a plethora of intrinsic and extrinsic signals capable of triggering an inflammatory response and activation of cell signings, such as the JNK and NF-kB signaling pathways and the target genes, e.g., IL-6, TNFα, interferons, and MCP-1." (PMID 38541912, 2024). "And, IL-6 may have diverse effects in the pathogenesis of obesity and hypertension, depending on the presence or absence of these conditions." (PMID 38615012, 2024). "The serum levels of CRP and IL-6 were higher in the sarcopenic obesity group, while the serum glucose was significantly higher in patients with obesity without sarcopenia than in the sarcopenic obesity group." (PMID 38921440, 2024).
Obesity (continued). "As obesity is known as a chronic proinflammatory state, the latest research also has proven higher levels of inflammatory cytokines such as C-reactive protein or interleukin 6 (IL-6) in depressed individuals compared to non-depressed adolescents." (PMID 38892598, 2024). "In contrast to IL6, IL1B is not up-regulated in the IFP of end-stage KOA patients which can explain why our study could not find any correlation between obesity-linked systemic factors and IL1B gene expression." (PMID 38694906, 2024). "In a meta-analysis of 48 prospective non-randomized studies, the authors reported that BS decreases the low-grade inflammation associated with obesity as measured by C-reactive protein (CRP) and interleukin 6, but not by tumor necrosis factor α, after pooling groups at 6 and 12 months follow-up." (PMID 39574780, 2024). "In children with obesity, FFA and adipokines (e.g., leptin) secreted by enlarged adipocytes promote the differentiation of monocytes to proinflammatory macrophages in adipose tissues, leading to the production of inflammatory cytokines including TNF-α and IL-6." (PMID 40302954, 2024). "This study found that while calorie restriction improved walking speed, especially in individuals with obesity and high IL-6 levels, the reduction in BMI was the main factor for this improvement, and changes in IL-6 levels did not significantly impact walking speed." (PMID 39766314, 2024). "Regarding inflammation, different kinds of cytokines, including interleukin-6 (IL-6), C-reactive protein (CRP), tumor necrosis factor α (TNF-α), as well as adipokines, may be involved in inflammatory pathways producing obesity and insulin resistance, triggering systemic stress." (PMID 38541047, 2024). "Additionally, obesity, asignificant factor in the development of T2DM, reduces the levels of adiponectin,a hormone that normally inhibits proinflammatory cytokines such as tumor necrosisfactor alpha (TNF-α) and interleukin 6 (IL-6)." (PMID 39742220, 2024). "IL6 and CCL4 may play important roles in the microenvironment of obesity and GC." (PMID 39011399, 2024). "For instance, elevated levels of IL-6 have been positively correlated with the expansion of adipose tissue.TNF-α, IL-6, and IL-1β can enhance the inflammatory cascade reaction and promote inflammatory responses, which are considered key triggering factors for obesity-related complications." (PMID 38453770, 2024). "Additionally, 49.7% of the cohort was affected by obesity, known to exacerbate inflammatory cytokine expression, as excess adipose tissue secretes elevated levels of pro-inflammatory adipokines like TNF-α and IL-6." (PMID 39408907, 2024). "Higher levels of IL-1β (A, p < 0.0001), IL-6 (B, p < 0.0001), IP-10 (E, p < 0.001), GM-CSF (F, p < 0.0001), TNF-α (G, p < 0.0001), and IFN-γ (H, p < 0.0001), and lower IL-10 levels (I, p < 0.05) were found in the volunteers with obesity compared with the NW group." (PMID 39125408, 2024). "Additionally, data related to plasma cytokines confirm these increases in TNF-α and IL-6 in animals with obesity and without treatment." (PMID 37445834, 2023). "A large body of evidence suggests that inflammatory cytokines such as TNF-α, IL-1β, and IL-6 not only induce systemic insulin resistance but also affect lipid metabolism, whereas the presence of IL-10 effectively improves insulin sensitivity and HFD-induced obesity." (PMID 38162665, 2023). "Adipose tissue, which expands and undergoes remodeling during obesity, contributes to vascular EC dysfunction by secreting vasoconstrictor mediators and proinflammatory cytokines such as TNF-α, interferon-gamma (IFNγ), interleukin-1β (IL-1β), and interleukin-6 (IL-6)." (PMID 37174741, 2023). "In obesity, an altered balance towards increased pro-inflammatory adipokines like TNF-α, IL-6 and IL-8 is present and may mediate the obesity-related state of inflammation of obese patients and favor the onset of metabolic disturbances and their increased cardiovascular risk." (PMID 37571368, 2023).